GNAI1 (G protein subunit alpha i1)
Description:
Guanine nucleotide-binding proteins (G proteins) function as transducers downstream of G protein-coupled receptors (GPCRs) in numerous signaling cascades. The alpha chain contains the guanine nucleotide binding site and alternates between an active, GTP-bound state and an inactive, GDP-bound state. Signaling by an activated GPCR promotes GDP release and GTP binding. The alpha subunit has a low GTPase activity that converts bound GTP to GDP, thereby terminating the signal. Both GDP release and GTP hydrolysis are modulated by numerous regulatory proteins. Signaling is mediated via effector proteins, such as adenylate cyclase: inhibits adenylate cyclase activity of ADCY1, ADCY5 and ADCY6, leading to decreased intracellular cAMP levels. The inactive GDP-bound form prevents the association of RGS14 with centrosomes and is required for the translocation of RGS14 from the cytoplasm to the plasma membrane. Required for normal cytokinesis during mitosis. Required for cortical dynein-dynactin complex recruitment during metaphase.
Synonyms: Gi; HG1B; NEDHISB
Tractability: Small molecule: a structure with a bound ligand is known; it has a binding pocket of medium quality. Antibody: UniProt places it where antibodies can reach, with high confidence; its Gene Ontology location is reachable by antibodies, with high confidence. PROTAC: ubiquitination databases record sites on it; its protein half-life has been measured; a small molecule that binds it is known.
Target class: Other membrane protein
Gene: Protein-coding gene on chromosome 7 (79,768,028 to 80,226,181, forward strand). Ensembl gene ENSG00000127955.
Subcellular location: Cell membrane; Nucleus; Cytoplasm; Cytoplasm, cytoskeleton, microtubule organizing center, centrosome; Cytoplasm, cell cortex
Subcellular location (Human Protein Atlas): Centrosome; Principal piece; Basal body; Centriolar satellite; Cytosol; Golgi apparatus; Nucleoli; Nucleoplasm
Pathways (Reactome):
Signal Transduction: Extra-nuclear estrogen signaling; G alpha (i) signalling events; G alpha (s) signalling events; G alpha (z) signalling events; GPER1 signaling
Metabolism: Adrenaline,noradrenaline inhibits insulin secretion; Regulation of insulin secretion
Disease: ADORA2B mediated anti-inflammatory cytokines production
Hemostasis: ADP signalling through P2Y purinoceptor 12
Neuronal System: Adenylate cyclase inhibitory pathway
Gene Ontology:
Molecular function: adenylate cyclase inhibitor activity; D2 dopamine receptor binding; G protein activity; GTP binding; GTPase activity; protein binding; G protein-coupled receptor binding; G protein-coupled serotonin receptor binding; G-protein beta/gamma-subunit complex binding; GDP binding; magnesium ion binding; guanyl nucleotide binding
Biological process: adenylate cyclase-inhibiting dopamine receptor signaling pathway; adenylate cyclase-inhibiting G protein-coupled receptor signaling pathway; adenylate cyclase-inhibiting serotonin receptor signaling pathway; cell division; chemokine-mediated signaling pathway; G protein-coupled receptor signaling pathway; interleukin-8-mediated signaling pathway; mast cell degranulation; neuropeptide signaling pathway; positive regulation of cholesterol biosynthetic process; positive regulation of protein localization to cell cortex; regulation of mitotic spindle organization; response to prostaglandin E; T cell migration; adenylate cyclase-activating G protein-coupled receptor signaling pathway; adenylate cyclase-modulating G protein-coupled receptor signaling pathway; cellular response to forskolin; establishment of mitotic spindle orientation; positive regulation of relaxation of smooth muscle; regulation of G protein-coupled receptor signaling pathway; response to peptide hormone; regulation of eating behavior; signal transduction
Cellular component: cell cortex; centrosome; cytoplasm; cytoplasmic side of plasma membrane; cytosol; extracellular exosome; heterotrimeric G-protein complex; lysosomal membrane; midbody; plasma membrane; spindle pole; membrane; nucleus
Genetic constraint (gnomAD): Loss-of-function variants: 2 observed, 10.04 expected, observed/expected ratio (o/e) 0.2, 90% interval 0.08 to 0.63. The synonymous counts are far from expectation, so gnomAD's model fits this gene poorly and the ratio says little. Missense variants: 143 observed, 147.72 expected, observed/expected ratio (o/e) 0.97, 90% interval 0.84 to 1.11. Synonymous variants: 72 observed, 53.81 expected, observed/expected ratio (o/e) 1.34, 90% interval 1.11 to 1.63.
Gene-disease validity (ClinGen):
ClinGen rates the evidence that GNAI1 causes each of these diseases.
complex neurodevelopmental disorder (autosomal dominant): Definitive. A disorder that involves more than one phenotype associated with the central nervous system, including but not limited to intellectual disability, autism, and seizures (epilepsy).
Homologues: Orthologues: chimpanzee GNAI1 (100% identical), dog GNAI1 (100% identical), macaque GNAI1 (100% identical), mouse Gnai1 (100% identical), pig GNAI1 (100% identical), tropical clawed frog gnai1 (98% identical), rabbit GNAI1 (96% identical), zebrafish gnai3 (91% identical), rat Gnai1 (90% identical), guinea pig GNAI1 (90% identical), Caenorhabditis elegans gpa-3 (49% identical), Caenorhabditis elegans gpa-11 (44% identical), and 9 more. Paralogues in human: GNAI3 (94% identical), GNAI2 (88% identical), GNAO1 (72% identical), GNAT2 (69% identical), GNAT3 (68% identical), GNAT1 (68% identical), GNAZ (67% identical), GNAQ (53% identical), GNA14 (53% identical), GNA11 (52% identical), GNAL (45% identical), GNA15 (44% identical), and 3 more.
Diseases named in the same sentence as GNAI1 in open-access papers:
GNAI1 is named in the same sentence as 63 diseases in open-access papers, as found by Europe PMC text mining. Sharing a sentence is not in itself a finding about the gene and the disease. The quoted sentences say what the papers report.
colorectal cancer (7 papers, 2021 to 2025). A primary or metastatic malignant neoplasm that affects the colon or rectum. "Moreover, reduced expression of GNAI1 has been notably associated with human colitis-associated colorectal cancer (CAC)." (PMID 39695099, 2024). "Reduced GNAI1 expression has been reported in hepatocellular carcinoma, where it is associated with increased tumor cell migration and invasion, as well as in colorectal cancer metastasis, where its loss enhances angiogenesis through activation of JAK2/STAT3 signaling and upregulation of VEGFA." (PMID 41550951, 2025). "In colorectal cancer models, exosomal miR-320d has been shown to downregulate GNAI1 expression in vascular endothelial cells." (PMID 40906190, 2025). "This study further validates the role of GNAI1 in promoting angiogenesis in colorectal cancer through its influence on STAT3 activity." (PMID 39695099, 2024). "In this study, we have demonstrated that exosomal miR-320d derived from colorectal cancer cells enhances angiogenesis in vascular endothelial cells and promotes cancer cell metastasis by downregulating GNAI1 expression, enhancing JAK2/STAT3 protein phosphorylation, and increasing VEGFA expression." (PMID 39695099, 2024). "Future studies involving metabolic flux analysis, DNA damage assays, and drug treatment experiments are warranted to explore these hypotheses and further elucidate the mechanistic roles of GNAI1 and GNAI2 in colorectal cancer biology and therapy response." (PMID 40819057, 2025). "GNAI1 (G Protein Subunit Alpha I1) has been identified as a potential biomarker in multiple tumors, such as ovarian cancer, colorectal cancer, and renal cell carcinoma, but its role in AS has not yet been reported." (PMID 33996893, 2021).
breast carcinoma (6 papers, 2017 to 2025). "For instance, low GNAI2 expression correlates with trastuzumab resistance in HER2-positive breast cancer, while GNAI1 overexpression has been linked to poor survival and chemoresistance in advanced-stage ovarian tumors." (PMID 40819057, 2025). "We identified 7 genes (ITGB1, SNAI1, NOTCH4, STAT5B, RAPGEF3, LAMA2, and GNAI1) that have been implicated in both stemness and the drug response and validated their relevance through an analysis of data from breast cancer patients in the TCGA database using UCSC Xena." (PMID 39180549, 2024). "The investigation found that GNAI1 expression was significantly lower across all subtypes and stages of breast cancer." (PMID 38326326, 2024). "According to data retrieved from the Ualcan TCGA base online tool, GNAI1 was profoundly downregulated in breast cancer." (PMID 38326326, 2024). "Furthermore, data obtained from the Gepia online tool's Pearson correlation analysis showed that B4GALT1-AS1 and GNAI1 were positively and significantly correlated in breast cancer." (PMID 38326326, 2024). "Previous studies have shown that GNAI2 regulates EMT in pancreatic and breast cancer via ERK signaling, and GNAI1 impacts DNA damage repair via ATM/CHK2 pathway modulation in glioblastoma." (PMID 40819057, 2025).
colon cancer (6 papers, 2020 to 2025). "Direct studies linking GNAI1 to retinal diseases are limited, but it has been linked to colitis, colon cancer, seizures, hypotonia, and neurodevelopmental disorders." (PMID 40906190, 2025). "It has been reported that IL-6 activates expansion of MDSCs via the JAK2/STAT3/NF-κB signaling pathway, resulting in AOM/DSS-induced colon tumor development in G protein subunit alpha i1 (GNAI1) and GNAI3 (GNAI1;3) double-knockout (DKO) mice." (PMID 33384962, 2020). "Moreover, GNAI1 could act as a tumor suppressor in colon cancer by regulating the IL6 signaling pathway." (PMID 35669499, 2022). "In a mouse model, GNAI1 and GNAI 3 suppressed DSS-plus-azoxymethane-induced colon tumor development, whereas the expression of GNAI2 in CD11c+ cells and interleukin-6 (IL6) in CD4+/CD11b+ dendritic cells appeared to promote these effects." (PMID 35743732, 2022).
hepatocellular carcinoma (6 papers, 2012 to 2025). A malignant tumor that arises from hepatocytes. "In hepatocellular carcinoma, overexpression of GNAI1 significantly reduced metastatic capability by interfering with the RhoA-ROCK signaling pathway, a known regulator of cytoskeletal remodeling and cell motility." (PMID 40819057, 2025). "Previous studies have demonstrated that the expression level of GNAI1 correlates with aggressive characteristics and unfavorable prognosis in gastric cancer and hepatocellular carcinoma." (PMID 39695099, 2024). "GNAI1 has been confirmed as an oncogene and therapeutic target in serous ovarian cancer and hepatocellular carcinoma." (PMID 36081671, 2022). "However, the biological functions of GNAI1 in hepatocellular carcinoma (HCC) remain unclear." (PMID 23691483, 2012).
developmental delay (4 papers, 2021 to 2025). "Mutations in the GNAI1 gene, which encodes Gαi1, cause a disorder characterized by developmental delay, intellectual disability, hypotonia, and epilepsy." (PMID 40894620, 2025). "GNAI1-associated neurodevelopmental disorder (GNAI1-NDD) is characterized by developmental delay, intellectual disability, hypotonia, epilepsy, and neurobehavioral symptoms, especially those specific to ASD (stereotyped movements, sensory sensitivity, anxiety, hyperactivity, inattention)." (PMID 40873676, 2025). "Additionally, GNAI1 variants are associated with developmental delay, intellectual disability, motor and language delay, hypotonia, and epilepsy." (PMID 40873676, 2025). "In a further similarity to Gαo, de novo point mutations in GNAI1, some of them—in the same positions as those found in GNAO1 mutant patients, have recently been described to cause dominant infantile neurological disorders with variable degrees of developmental delay, seizures, and hypotonia." (PMID 34685729, 2021).
epilepsy (4 papers, 2025). A brain disorder characterized by episodes of abnormally increased neuronal discharge resulting in transient episodes of sensory or motor neurological dysfunction, or psychic dysfunction. "There is growing evidence that GNAI1 plays a role in human platelet aggregation, signal transduction of rat liver trypsin receptor, paclitaxel resistance of human ovarian cancer cells, hypotonia and epilepsy." (PMID 40442789, 2025).
glioma (4 papers, 2020 to 2025). A benign or malignant brain and spinal cord tumor that arises from glial cells (astrocytes, oligodendrocytes, ependymal cells). "In gliomas, overexpression of GNAI1 or GNAI3 appears essential for AKT hyperactivation and tumor growth." (PMID 34321466, 2021). "Similar to GPC3, some scholars believe that GNAI1 is a tumor-promoting gene and reported up-regulated GNAI1 mRNA in human glioma, which is inconsistent with our data." (PMID 32766727, 2020). "A previous study demonstrated the crucial role of YME1L within glioma cells in facilitating the transcription and expression of G protein subunit alpha i1 (Gαi1), a key protein essential for the activation of Akt-mTOR cascade through various receptor tyrosine kinases (RTKs) and non-RTK receptors." (PMID 38769124, 2024).
ovarian carcinoma (4 papers, 2021 to 2025). A malignant neoplasm originating from the surface ovarian epithelium. "In line with this, previous studies have reported GNAI1 downregulation as a poor prognostic marker in ovarian cancer and GNAI3 suppression associated with metastasis in gastric cancer." (PMID 40819057, 2025). "Literature search reveals that GNAI1 is involved in prostate cancer growth and GNAI2 is essential in prostate cancer cell migration and invasion and is also a crucial regulator in another hormone-dependent cancer, ovarian cancer." (PMID 38983753, 2024).
colitis (3 papers, 2021 to 2025). Inflammation of the colon. "Knockout GNAI1 and GNAI3 in BMDSCs cells can induce phosphorylation of JAK2 and STAT3, promoting colitis-associated tumors in mice." (PMID 39695099, 2024). "For example, GNAI1 and GNAI3 were found to reduce colitis-associated tumorigenesis in mice through blocking of IL6 signaling and down-regulation of the expression of GNAI2." (PMID 34992636, 2021).
gastric cancer (3 papers, 2024 to 2025). A primary or metastatic malignant neoplasm involving the stomach. "In addition, PINK1.AS promoted gastric cancer progression by sponging miR-200a to negatively regulate the expression of G Protein Subunit Alpha I1 (Gαi1) expression." (PMID 38326441, 2024).
bladder cancer (2 papers, 2023). "GNAS and GNAI1 were not differentially expressed in recurrent bladder cancer samples, although these were associated with the 5hmC DMR in the promoter regions." (PMID 37138354, 2023).
ciliopathies (2 papers, 2025). "Given the overlap in clinical features observed in classic ciliopathies and GNAI1 disorder (Neurodevelopmental disorder with hypotonia, impaired speech, and behavioral abnormalities; OMIM # 619854), we first wondered whether GNAI1 may play a role in cilia assembly." (PMID 40894620, 2025). "Given the overlap in clinical features observed in classic ciliopathies and GNAI1 disorder (NDD with hypotonia, impaired speech, and behavioral abnormalities; OMIM # 619854), we first wondered whether GNAI1 may play a role in cilia assembly." (PMID 41052774, 2025).
melanoma (2 papers, 2019 to 2025). A malignant, usually aggressive tumor composed of atypical, neoplastic melanocytes. "Our results showed that THOC2 inhibition significantly reduced the expression of PDE4D, PIK3CA, GNAI1, ADCY1, HHIP and ADORA2A in melanoma cells." (PMID 31680623, 2019). "THOC2 expression was positively correlated with PDE4D, PIK3CA, GNAI1, and HHIP expression in melanoma tissues." (PMID 31680623, 2019). "Notably, the inhibition of the miRNAs in the resistant cell lines increased the expression of GNAI1 and NR6A1 and reduced melanoma cell growth." (PMID 41550951, 2025). "GNAI1, ADCY1 and NR6A1 common target genes involved in the restriction of cAMP signal transduction and of the activation of mTOR pathway signaling were identified among the target genes in the lipid metabolism pathways dysregulated in resistant melanoma cells." (PMID 41550951, 2025). "In addition, correlation analysis showed that THOC2 expression was correlated with PDE4D, PIK3CA, GNAI1, and HHIP expression in melanoma tissues." (PMID 31680623, 2019).
thyroid cancer (2 papers, 2020). "GNAI1 was reported to confer hydrogen peroxide-induced apoptosis in human lung cancer cells and be associated with the prognosis of thyroid cancer patients." (PMID 33330065, 2020). "Among the top 30 hub genes obtained in PPI network, the expression levels of FN1, NMU, CHRDL1, GNAI1, ITGA2, GNA14 and AVPR1A were associated with the prognosis of thyroid cancer." (PMID 32337286, 2020). "The Human Protein Atlas (HPA)-based Immunohistochemistry (IHC) database showed that FN1, NMU, and ITGA2 were upregulated in thyroid cancer tissues compared with normal tissues, while CHRDL1, GNAI1 and GNA14 were downregulated in thyroid cancer tissues." (PMID 32337286, 2020). "Using data mining based on bioinformatics tools, the present study has confirmed CHRDL1, GNAI1, GNA14 and AVPR1A are associated with thyroid cancer although their specific biological functions have not been explored by the molecular biology methods." (PMID 32337286, 2020). "Hence, we derived seven key genes related to the prognosis of thyroid cancer: FN1, NMU, CHRDL1, GNAI1, ITGA2, GNA14, AVPR1A." (PMID 32337286, 2020).
autoimmune disease (1 paper, 2019). A disorder resulting from loss of function or tissue destruction of an organ or multiple organs, arising from humoral or cellular immune responses of the individual to their own tissue constituents. "The identified targets TGFBR1 and IGF1R have been shown to be downregulated in blood cells of patients with autoimmune disease and a loss of SP1 and knockdown of GNAI1 have been described to impair hematopoiesis and immune cell migration capability, respectively." (PMID 31569706, 2019).
cocaine addiction (1 paper, 2022). "There were 13 genes enriched in cocaine addiction and the circadian entrainment signaling pathway (Bdnf, Gnai1, Gnai3, Grin2d, Grm2, Maob, Cam2, Camk2g, Gng12, Mapk1, Pcb4, Prkm2, and Pdyn)." (PMID 36164400, 2022).
encephalopathies (1 paper, 2021). "Among the amino acids found mutated both in the GNAO1- and GNAI1-encephalopathy, the Gln52Pro mutations have been identified." (PMID 34685729, 2021). "Recently, a number of mutations in a related gene GNAI1, many of them identical to those in the GNAO1-encephalopathy, have been described to cause similar clinical manifestations in children." (PMID 34685729, 2021). "We wish to underline that the incompetence to interact with guanine nucleotides we ascribe to the Gln52 mutations in GNAO1 and GNAI1 is unlikely to be the general molecular feature for all the >30 point mutations identified in either gene in the pediatric encephalopathy patients." (PMID 34685729, 2021). "We show that, unlike other previously characterized encephalopathy variants, mutations in the Gln52 result in a loss of basic biochemical and cellular activities of the Gα-subunits, providing a novel basis for the molecular etiology of the GNAO1- and GNAI1-related pediatric encephalopathies." (PMID 34685729, 2021).
Hyperglycemia (1 paper, 2020). An increased concentration of glucose in the blood. "With OLAN treatment, in addition to its induction of INPP5D, the suppression of AMY2B and GNAI1 are predicted to increase hyperglycemia and decrease insulin sensitivity." (PMID 33302598, 2020).
nicotine dependence (1 paper, 2020). Physical and psychological dependence on nicotine. "We observe five genome-wide significant loci, including previously unreported loci MAGI2/GNAI1 (rs2714700) and TENM2 (rs1862416), and extend loci reported for other smoking traits to nicotine dependence." (PMID 33144568, 2020).